UGDH (UDP-glucose 6-dehydrogenase)
Diseases named in the same sentence as UGDH in open-access papers (continued):
Sharing a sentence is not in itself a finding about the gene and the disease.
tumor (29 papers, 2011 to 2025). "As a necessary element in HA formation, UGDH knock down (UGDH KD) is shown to decrease HA formation and thus alter the associated aggressive tumor microenvironment phenotype." (PMID 37769033, 2023). "On the other hand, we studied the association of silencing UGDH with the generation of an ECM that favors tumor development and resistance." (PMID 33572239, 2021). "Our results demonstrated that the shRNA‐mediated deficiency of UGDH significantly decreased tumour growth." (PMID 32893977, 2020). "The knockdown of UGDH caused cell cycle arrest in the G0/G1 phase and induced a massive decrease of tumour formation rate in vivo." (PMID 32893977, 2020). "UGDH is also implicated in tumor progression and osteoarthritis." (PMID 21984906, 2011). "Thus, we hypothesized that a deficiency in UGDH would influence the tumour growth rate in a xenograft model." (PMID 32893977, 2020). "This functional cluster of proteins was also identified by proteins involved in proteoglycan metabolism: in addition to lumican, decorin, and mimecan, UDP-glucose 6-dehydrogenase (UDP-GlcDH) was also identified, with the lowest level in the tumor." (PMID 39195201, 2024). "This analysis led to the identification of genes generally associated with cancer cells (MUC1, LGALS3, UGDH, TSTA3, and GALE) or the stromal compartment (LGALS1, PSAP, LGALS9, IDS, and MGAT1) in most of the tumor types analyzed." (PMID 38384845, 2024). "Knockdown of UGDH improved survival and reduced tumor burden in C1/Mesenchymal compared to controls." (PMID 37858159, 2023). "In this review, we classify UGDH as a molecular indicator of tumor progression in multiple cancer types, describe its involvement in key canonical cancer signaling pathways, and identify methods to inhibit UGDH, its substrates, and its downstream products." (PMID 37769033, 2023). "UGDH knockdown decreases cell motility, invasion, glycosaminoglycan biosynthesis, cell migration, tumor growth, hyaluronic acid production, and colony formation and induces cell cycle arrest in the G0/G1 phase." (PMID 37834160, 2023). "This suggests that UGDH expression is important for tumor establishment and outgrowth in the C1/MES subtype." (PMID 37858159, 2023). "In this review, the role of UGDH in tumor progression across various cancers and the on-going efforts to pharmacologically target UGDH are discussed." (PMID 37769033, 2023). "UGDH promotes tumor metastasis by increasing the stability of snail family transcriptional repressor 1 mRNA." (PMID 37667226, 2023). "Given the well-established association between high levels of UGDH and aggressive, metastatic tumor phenotypes across many cancers, there is significant potential to use UGDH as both a prognostic marker and therapeutic target in clinical settings." (PMID 37769033, 2023). "In this study, we found that the abilities of GSTZ1 deficiency‐mediated UGDH up‐regulation, UDP‐GlcUA accumulation, and tumour migration promotion were NRF2 dependent." (PMID 35979621, 2022). "Lower GSTZ1 and E‐cadherin levels and higher UGDH and pSmad2/3 levels were observed in tumour samples than in adjacent non‐tumoural tissues." (PMID 35979621, 2022). "Several studies have recently reported that UGDH is involved in tumour growth, metastasis and patient survival." (PMID 34942055, 2022). "The fact that low expression of HAS2 is correlated with lower tumour cell growth is strengthened by the results of String analysis that HAS1-3 interact close with UGDH." (PMID 35767191, 2022). "Recently, a growing number of studies have focused on UGDH in cancer, and the roles of UGDH in tumour growth, metastasis and patient survival have been well documented." (PMID 34942055, 2022). "In turn, different studies have analyzed the role of UGDH as a marker of tumor progression during chemotherapy with drugs that are eliminated by glucuronidation." (PMID 33572239, 2021).
tumor (continued). "It is important to highlight that we found by cytometric analysis two well-differentiated populations of tumor cells with different ability to accumulate EPI after silencing the UGDH enzyme." (PMID 33572239, 2021). "Together, these results support a role for elevated UGDH in driving androgen independent tumor cell growth through altered use of UDP-sugar metabolites." (PMID 34548906, 2021). "We found that LC3-II protein levels were even higher when the UGDH enzyme was silenced before treating tumor cells with EPI." (PMID 33572239, 2021). "In turn, we observed that tumor cells not only conserved their migratory ability under those conditions but also increased migration levels even under UGDH knockdown and EPI treatment." (PMID 33572239, 2021). "On the contrary, a significant pro-tumoral effect was visualized in response to the silencing of UGDH when we analyzed angiogenesis and tumor migration." (PMID 33572239, 2021). "IHC staining of the tumour sections confirmed the lower expression level of UGDH in the UGDH knockdown group compared to in the control group, indicating the long‐term inhibition via shRNA in our injected cells." (PMID 32893977, 2020). "An underlying dependence of CR tumor cells for energy metabolism pathways such as enhanced expression of GLDC, ACC, ASNS, FDFT1, UGDH, PYCR2, etc was noted." (PMID 27470985, 2016). "Overproduction of proteoglycans has been implicated in the progression of certain epithelial cancers, while inhibition of UGDH diminished tumor angiogenesis in vivo." (PMID 21984906, 2011). "Inhibition of hUGDH has been demonstrated to diminish tumor angiogenesis in vivo, while UGDH gene disruption in zebrafish led to a heart valve defect." (PMID 21984906, 2011). "Overall, our results support UGDH phosphorylation as a point of control for intracellular and cell surface glycan production, thereby regulating cell proliferation, anchorage dependence, motility, and tumor cell therapeutic resistance." (PMID 41110727, 2025). "Notably, the ER+ tumor group demonstrated a considerably higher abundance of C1 UGDH+ TCs in comparison to the Normal group." (PMID 40114930, 2025). "The effect of UGDH knockdown or overexpression in the C1/ Mesenchymal and C4/Differentiated subtypes respectively was tested on mouse intrabursal xenografts and showed dynamic changes to the tumor stroma." (PMID 37858159, 2023). "Multiple studies have demonstrated UGDH’s clinical relevance to the field of oncology, and this review summarizes the evidence implicating UGDH as a candidate biomarker of aggressive cancer phenotypes and/or a potential therapeutic target to mitigate tumor progression and enhance patient survival." (PMID 37769033, 2023). "Within the OV90 xenografts, UGDH knockdown significantly reduced tumor burden compared to controls." (PMID 37858159, 2023). "The idea that UGDH activity could be involved in “tumor-like” changes observed in rheumatoid synovium is a hypothesis that warrants further investigation." (PMID 36107941, 2022). "These investigations suggest that the tumour promoting effects of UGDH may in part be attributed to changes in choline metabolism." (PMID 34942055, 2022). "The upregulation of the expression of UGDH could promote the elimination of this cytotoxic drug from tumor cells." (PMID 33572239, 2021). "Together, these results indicate that, despite being under an anti-tumoral treatment and with less availability of the UGDH enzyme, tumor cells activate several mechanisms directly related to tumor progression and drug resistance, despite the cells reducing its glucuronidation and/or elimination." (PMID 33572239, 2021). "Since the differences found in the expression of LC3-II indicated a possible positive modulation of autophagy in response to EPI treatment, we decided to continue analyzing the formation of autophagosomes in tumor cells after UGDH silencing and treatment with EPI." (PMID 33572239, 2021).
tumor (continued). "Furthermore, the tumour weights in mice implanted with TOV21GHI cells expressing UGDH shRNA were sixfold lighter than those in mice implanted with TOV21GHI cells expressing the empty vector." (PMID 32893977, 2020). "UGDH inhibition has been claimed to diminish tumor angiogenesis in vivo." (PMID 29707113, 2018). "In particular, this included genes involved in secretory pathways, lipid and sugar metabolism (such as, UGDH, SORD, GLUD1, ELOVL5, ASCL3, UAP1), but also genes implicated in tumor progression and metastasis with functions in cell survival, proliferation and adhesion (EHF, ELL2, TPD52, MAFB, SGK)." (PMID 21829708, 2011). "To define the clinical relevance of our findings, we determined the levels of UGDH, GSTZ1, pSmad2/3 and E‐cadherin in tumours from 10 HCC patients with metastatic recurrence." (PMID 35979621, 2022). "Using this model, we compared the impact of UGDH manipulation on AR-mediated gene expression, proteoglycan production, glucuronidation enzymes, UDP-sugar metabolites, and the proliferation rates of tumor cells." (PMID 34548906, 2021). "All seven glucose metabolism-related proteins were downregulated in SBP1 induced-tumor tissue, including GAA, GAPDH, ALDH2, Thioredoxin, ENO3, UGDH and Lumican." (PMID 25974208, 2015). "In comparison, overexpression of UGDH in the ACI23 xenografts did not significantly affect tumor size." (PMID 37858159, 2023). "We show UGDH promotes TIC survival and that targeting this enzyme in the highly aggressive mesenchymal molecular subtype reduces viability post-chemotherapy in vitro and tumor growth in vivo." (PMID 37858159, 2023). "The role of UGDH and its downstream product UDP-GlcUA in producing ECM precursors HA, proteoglycans (PGs) and other glycosaminoglycans (GAGs) is particularly salient to studies assessing tumor aggression and migratory capacity." (PMID 37769033, 2023). "In vivo, overexpression of UGDH in ACI23 xenografts did not significantly affect tumor size or necrosis." (PMID 37858159, 2023). "UGDH-mediated EMT gene expression is not shown to consistently modulate migratory phenotypes across all tumor types." (PMID 37769033, 2023). "Additionally, 4-MU and UGDH knockdowns were shown to increase anti-tumor immune responses in GBM in vitro and in vivo by activating phagocytosis in tumor-residing macrophages, decreasing immune-suppressing regulatory T-cell activity, and increasing cytotoxic T-cell infiltration and activation." (PMID 37769033, 2023). "Another alternative hypothesis could be that EPI is in its inactive form, conjugated to UDP-GlcUA from a source that does not depend on UGDH, for example, from the degradation of HA present in the tumor ECM." (PMID 33572239, 2021). "Thus, elevated UGDH expression is likely not a trigger for tumour initiation, but tumorigenic cells may rely on UGDH to facilitate tumorigenicity and malignancy." (PMID 34942055, 2022). "Hence, it is not surprising that UGDH, which is involved in the synthesis of hyaluronan precursor UDP-glucuronic acid, is elevated several-fold in CR tumor cells." (PMID 27470985, 2016).
cancer (23 papers, 2010 to 2025). A tumor composed of atypical neoplastic, often pleomorphic cells that invade other tissues. "Along with its relationship to downstream signaling pathways, UGDH has a key role in glucose/UDP-sugar metabolic pathways associated with cancer progression." (PMID 37769033, 2023). "A top hit was the cancer-associated, proteoglycan subunit synthesis enzyme UDP-glucose dehydrogenase (UGDH)." (PMID 37858159, 2023). "Besides, our purpose was to postulate the UGDH enzyme and HA-associated genes as prognostic biomarkers in this type of cancer." (PMID 33572239, 2021). "Concerning the ELOVL1, UGDH and HSP90AA1, studies only showed the correlation with cancer, and further exploration is needed to elucidate the underlying mechanisms." (PMID 36632140, 2023). "The importance of UGDH in human cancer is a topic of recent interest, both from a mechanistic and prognostication standpoint." (PMID 37769033, 2023). "UGDH frequently overexpressed in various cancers and shown to be involved in cancer progression through both HA-dependent and independent mechanisms." (PMID 37169760, 2023). "While there are not many, some studies have presented alternative strategies to inhibit UGDH activity in cancer cells." (PMID 37769033, 2023). "As a catalyst of rate-limiting steps in several pro-tumorigenic pathways within cancer cells, UGDH, along with its substrates and downstream products, present promising targets for drug discovery." (PMID 37769033, 2023). "Most studies exploring the relationship amongst UGDH, glucuronidation, and cancer have been conducted in hormonally responsive cancers such as prostate and breast." (PMID 37769033, 2023). "As such, we position UGDH as an enzyme to be exploited as a potential prognostication marker in oncology and a therapeutic target in cancer biology." (PMID 37769033, 2023). "UGDH inhibitors, such as 4‐MU and quercetin, have also received increased attention in potential cancer therapeutic strategies." (PMID 35979621, 2022). "To account for UGDH in cancer progression and oncogenesis, we compared results from the EMT models to UGDH functions in the tumorigenic breast mesenchymal cell lines D492HER2 and MDA‐MB‐231." (PMID 34942055, 2022). "We further studied the downstream functions of the metabolic enzyme UGDH in cancer progression and metabolism, and finally, we explored the upstream signalling regulating UGDH." (PMID 34942055, 2022). "We further tested the RNA expression of UGDH, which showed the most changes to protein expression in all EMT models and was associated with cancer aggressiveness." (PMID 34942055, 2022). "A better understanding of the conformational changes occurring during the UGDH reaction cycle will pave the way for inhibitor design and potential cancer therapeutics." (PMID 21984906, 2011). "Interestingly, the survival of cancer cells overexpressing UGDH was shown to be critically dependent on the UDP-glucuronate decarboxylase 1 (UXS1) enzyme that converts toxic UDP-glucuronate to UDP-xylose." (PMID 39456684, 2024). "We next examined whether altered expression of UGDH in cancer cells could indirectly influence cells in the TME, using a co-culture of EOC cells and fibroblasts that allowed media exchange but not cell contact between fibroblasts and EOC cells." (PMID 37858159, 2023). "Thus, multiple cancer models demonstrate a direct link between UGDH activity, ECM precursor formation, and subsequent aggressive and metastatic oncologic phenotypes." (PMID 37769033, 2023). "Additionally, there has recently been more literature published on the potential role of UGDH in treatment resistance and immune modulation across various cancer types." (PMID 37769033, 2023). "This could mean that targeting the UGDH-HA pathway might expose therapeutic vulnerabilities of various cancers and lead to more efficient combination therapies involving both chemotherapies and immunotherapies." (PMID 37769033, 2023).
cancer (continued). "Results showing that targeting HA by 4-MU leads to anti-cancer effects in vivo show promise that UGDH targeting could have similar anti-cancer treatment." (PMID 37769033, 2023). "This suggests that in EOC, the function of UGDH in promoting cancer progression is not linked to distinct nuclear or cytoplasmic roles." (PMID 37858159, 2023). "Our findings align with previous reports of the effects of UGDH knockdown in cancer." (PMID 37858159, 2023). "The function of UGDH is largely characterized in human cancers." (PMID 37169760, 2023). "Paradoxically, this did not increase cytotoxicity; rather, UGDH KD was associated with increased autophagy of cancer cells, which is involved in the development of epirubicin resistance." (PMID 37769033, 2023). "Previous reports demonstrated that UGDH is involved in cell migration, but its specific role in cancer metastasis remains unclear." (PMID 32893977, 2020). "Cancers expressing high levels of UGDH and/or HA could benefit from 4-MU treatment." (PMID 37769033, 2023). "In addition, dysregulation of UGDH is central in various human cancer progression and metastasis." (PMID 37169760, 2023). "Potential explanations for the discrepancies between our results and that of Pitsillides is that the “normal” synovium from these former studies used cancer patient joints, and rheumatoid synovial lining cells may have inactivated UGDH due to intracellular ROS or peroxide." (PMID 36107941, 2022). "The UGDH and diaphorase enzyme staining technique described here could be readily applied to various cancer cell lines, and unfixed frozen cryosections from tumors, to provide information on cell types and subcellular location in which UGDH activity is enhanced." (PMID 36107941, 2022). "UGDH mRNA expression levels were significantly lower in CRC tissues than in normal tissues and can potentially serve as a prognostic indicator for this cancer, similar to the presented findings." (PMID 41465541, 2025). "‘Metabolic pathways’ include UDP-glucose 6-dehydrogenase (UGDH), tripartite motif containing 44 (TRIM44), and branched-chain amino acid transaminase 1 (BCAT1), and these genes are known to affect cancer development." (PMID 37667226, 2023). "Here we examined the expression and localization of UGDH in tissue microarrays of EOC histotypes mucinous, endometrioid, clear cell and serous, as well as in the molecular subtypes of high-grade cancers and report its prognostic value." (PMID 37858159, 2023). "In this study, we chose to pursue UGDH due to its medium–high expression in EOC compared to normal ovarian tissue, its inclusion in GSEA hallmarks that were enriched in spheroids and its reported roles in promoting cancer progression." (PMID 37858159, 2023). "As for cancer patient synovium, UGDH could be upregulated to serve another role such as supplying UDP-GlcA for glucuronidation and clearance of cancer medications." (PMID 36107941, 2022). "Furthermore, differentially quantified proteins (such as PGS2, UGDH, ASPN, LUM, COEA1, and PRELP) were found in comparisons of healthy and cancer breast tissues, suggesting potential utility of the All-in-One pipeline for the emerging application of proteomic cancer sub-typing." (PMID 36937585, 2023). "UDP‐glucose dehydrogenase (UGDH) is an enzyme that catalyses NAD+‐dependent two‐step oxidation of UDP‐glucose to generate UDP‐glucuronate, but its roles and detailed regulatory mechanisms in cancer progression remain unclear." (PMID 32893977, 2020).
infection (2 papers, 2021 to 2022). The state of being infected such as from the introduction of a foreign agent such as serum, vaccine, antigenic substance or organism. "Post-infection upregulated 20 transcripts in B-48, including G6PD (6 DEGs), GSDH (3 DEGs), GDPGP1 (4 DEGs), GPI (1 DEG), UGDH (1 DEG), UGPUT (3 DEGs), UGGT (1 DEG) and GPT2 (1 DEG)." (PMID 34948367, 2021).
cardiovascular diseases (1 paper, 2024). "Our primary focus is on their roles in cardiovascular diseases, the result uncovered involvement of ADK, BLVRA, ALDH1B1, UGDH, and HIBCH." (PMID 39369254, 2024).
neurological diseases (1 paper, 2020). "UGDH deficiency might parralel other neurological diseases with defects in GAG synthesis, modification, and degradation." (PMID 32001716, 2020).
UGDH also shares sentences with these, for which no sentence is quoted: clear cell ovarian cancer (2 papers); mucinous adenocarcinoma (2); Atrophy (1); cerebellar ataxia (1); colon cancer (1); cystic fibrosis (1); dilated cardiomyopathy (1); dry eyes (1); epilepsy (1); fatty liver (1); galactosaemia (1); head/neck cancer (1); Lissencephaly (1); mucinous ovarian carcinoma (1); Neurodevelopmental delay (1); neuropathy (1); Obesity (1); ovarian cystadenocarcinoma (1); pancreatic cancer (1); phenylketonuria (1); polycystic kidneys (1); retinal degeneration (1); rheumatoid arthritis (1); Seizure (1); speech disorder (1); squamous cell cancer lung cancer (1).